TNF (tumor necrosis factor)
Diseases named in the same sentence as TNF in open-access papers (continued):
Sharing a sentence is not in itself a finding about the gene and the disease.
breast carcinoma (continued). "To explore the impact of TNF-α-conditioned macrophage-derived extracellular vesicles (TNF EVs) on the growth of ER+ breast cancer cells, we evaluated the proliferation of MCF-7 cells after exposure to different TNF EV subpopulations and concentrations." (PMID 40567500, 2025). "This methodology has been effective in uncovering optimal drug targets in various contexts, including previously established targets for breast cancer (e.g., SRC, MTOR) and spinal cord injury (e.g., TNF, FOS, IL6)." (PMID 40895536, 2025). "This systematic review highlights consistent associations between increased pro-inflammatory cytokines (i.e., IL-6, IL-1β, TNF-α), reduced levels of hippocampal BDNF, and cognitive impairment in preclinical models of breast cancer and chemotherapy." (PMID 41155372, 2025). "The rationale for this is supported from our previous study in ER+ breast cancer models where the treatment with AURK and WEE1 kinase inhibitors resulted in the upregulation of TNFα signaling." (PMID 41285729, 2025). "Similar findings revealed that LPS‐activated monocytes release TNF‐α to induce endothelial ICAM‐1/VCAM‐1 expression, thereby facilitating breast cancer cell adhesion and metastatic progression." (PMID 40747615, 2025). "Experiments using breast cancer patient-derived xenografts revealed that paclitaxel treatment activates type I IFN and TNFα and that a cGAS-STING-dependent apoptotic effect is required for the paclitaxel response in vivo." (PMID 41299712, 2025). "An important mediator of TAMs function is Tumor Necrosis Factor-alpha (TNF-α), a pro-inflammatory cytokine that promotes both tumor growth and inflammation in the breast cancer microenvironment." (PMID 40567500, 2025). "For example: In ER + breast cancer (BC), Kv11.1 channel-induced senescence triggered SASP-dependent activation of CD4 + Th1 cells and memory T cells, leading to TNF-α-mediated killing of senescent tumor cells." (PMID 40781676, 2025). "For the in vitro models, we analyzed the B16 (mouse melanoma), EMT6 (mouse breast cancer), KPC (mouse pancreatic cancer), and MC38 (mouse colon cancer cells) models treated with IFNβ, IFNγ, and TNF-α." (PMID 38590654, 2024). "For example, triptolide sensitizes breast cancer cells to TNF-α-induced apoptosis by inhibiting the nuclear factor-kappa B NF-κB pathway, which is crucial for TNF-α signaling." (PMID 39457411, 2024). "In our study, we observed that CCT2 silencing in breast cancer cells led to enhanced activation (CD40L) and the proinflammatory cytokine (IFN-γ and TNFα) production in CD4+ T cells within the tumor microenvironment." (PMID 39079960, 2024). "A comprehensive profiling of histone modifications identified H3K36me2 as the most significantly upregulated epigenetic chromatin mark in the breast cancer cells, in response to TGF-β/TNF-α co-stimulation." (PMID 39351229, 2024). "Linalool improves Th1 cellular immunity in breast cancer cells by inducing the release of IFNG and TNF in lymphocytes." (PMID 39759512, 2024). "While the dependency on IFN-ɣ for CXCL9/10 induction was previously known, our data show the cooperation between IFN-ɣ and TNF-α in promoting the secretion of CCL5 and CXCL9 from breast cancer cells." (PMID 38167224, 2024). "Our in vitro data show that TNF-α and TGF-β cooperatively upregulate MMP-9 expression in breast cancer cells." (PMID 39351229, 2024). "TNF-α stimulates the stromal cells and releases elevated levels of CCL2, CXCL8, and CCL5, which have tumor-promoting solid activities in general and breast cancer, mainly when derived from stroma cells." (PMID 38541912, 2024). "Subsequent treatment with TNF-α results in caspase-8-mediated cleavage of GSDMC, leading to pyroptosis and tumor necrosis in breast cancer." (PMID 39300122, 2024).
breast carcinoma (continued). "Our results bear some similarities with those of a previous study showing that TGF-β1/TNF-α co-induced epithelial to mesenchymal transition (EMT) and invasiveness of breast cancer cells, through gradually increasing TGF-β receptors expression." (PMID 39351229, 2024). "Individually, MMP-9, TNF-α, and TGF-β are integral contributors in the complicated and multifaceted process of breast cancer metastasis." (PMID 39351229, 2024). "MMP-9, TNF-α, and TGF-β are integral contributors to the complicated and multifaceted process of breast cancer metastasis." (PMID 39351229, 2024). "Other studies have shown that C5AR1‐positive neutrophils can also release inflammatory factors such as IL1 β, TNF α and ENO1, which are known to promote tumour progression in breast cancer." (PMID 39580709, 2024). "To test the generalizability of our findings across different breast cancer cell lines, we treated breast cancer cell lines MCF-7 and T47D with TGF-β or TNF or TGF-β/TNF-α." (PMID 39351229, 2024). "The data from this study showed that high serum levels of TNFα and Groα/CXCL1 increased OR for breast cancer at age ≤ 50 and age > 50 years in both AA and LA women." (PMID 38541912, 2024). "siRNA-mediated knockdown of NSD2 in our breast cancer cell model significantly abolished the cooperativity between TGF-β and TNF-α for promoting MMP-9 expression, confirming the pivotal role of H3K36m2 chromatin active mark in this synergy." (PMID 39351229, 2024). "In the present study, we exposed breast cancer cells to the ELIT cocktail (17β-estradiol, leptin, IL6, and TNFα) simulating the hormonal and inflammatory conditions of postmenopausal obesity." (PMID 39767718, 2024). "Specifically, ganglioside GD3 synthase expression is necessary in breast cancer for the initiation and maintenance of EMT in TNF-α-induced changes to EMT." (PMID 38612859, 2024). "Using an MDA-MB-231 cell line model of breast cancer, we herein delve into the epigenetic mechanisms that drive the synergy between TGF-β and TNF-α, with implications for MMP-9 overexpression in the TME." (PMID 39351229, 2024). "Altogether, these results suggest that the H3K36 dimethylation plays a crucial role in MMP-9 gene regulation in breast cancer cells, induced by TGF-β/TNF-α co-stimulation." (PMID 39351229, 2024). "Co-culture of ovarian or breast cancer cells and TAMs can trigger the activation of nuclear factor kappa-B (NF-κB) and c-Jun N-terminal kinases (JNK) pathways in a TNF-α-dependent manner, which leads to increased invasion of tumor cells." (PMID 39003350, 2024). "Accordingly, CARTs secreted more IFN-γ, TNF-α, granzyme B and expressed more CD25, CD107a than blank-T cells when exposed to PDAC-CAFs, HCC-CAFs and PFs/breast cancer CAFs/colorectal cancer CAFs." (PMID 39086477, 2024). "Using a well-established MDA-MB-231 breast cancer model, we found that the synergy between TGF-β and TNF-α led to MMP-9 upregulation at the transcriptional and translational levels, compared to treatments with each agent alone." (PMID 39351229, 2024). "Within the TME, we have previously identified the ability of joint stimulation by estrogen, tumor necrosis factor α (TNFα) and epithelial growth factor (EGF) to profoundly elevate the content of CSCs in HR+/HER2− breast cancer cells." (PMID 37190183, 2023). "We explored various databases to correlate the expression patterns of TNF-α, NF-κB signaling and ATX (ENPP2) expression in breast cancers." (PMID 38201482, 2023). "IL-6, TGF-beta, TNF-alpha, NF-kB, COX-2 and PGE-2 are pro-inflammatory cytokines present in the TME of ER+ breast cancer that are capable to activate pro-tumoral pathways mediating proliferation, immune evasion and metastasis." (PMID 38332913, 2023). "The miRNA sequencing and enrichment analysis employed in this study have identified several crucial pathways involved in tumorigenesis, including miRNA in cancer, breast cancer, MAPK, RAS signaling, TNF signaling, and PI3K-Akt pathways." (PMID 37445965, 2023).
breast carcinoma (continued). "Inflammatory cytokines, such as IL-6 and TNF-α, have been found to upregulate ANXA1 expression in breast cancer cells." (PMID 37507468, 2023). "We investigated this role of inflammation in ATX and LPA signaling in the present study and established a link among TNF-α, NF-κB and ATX in breast cancer." (PMID 38201482, 2023). "Missing moderator variables for breast cancer were 0.3% for chemotherapy, 25.2% for IL6, and 24.8% for TNFα." (PMID 36658635, 2023). "Subsequent studies also elucidated the fact that AIF1 promotes breast cancer cell migration through the activation of the p38 MAPK signaling pathway, which upregulates the expression of tumor necrosis factor-α (TNF-α)." (PMID 37237507, 2023). "miR-125b, which is downregulated in breast cancer cells, also suppresses translation of the MUC1 oncoprotein, while miR-23a is considered to be involved in TNF-α-induced endothelial cell apoptosis." (PMID 37958720, 2023). "In normal breast epithelial and breast cancer cells, both IKK-β and NF-κB p65 were required for TNF-α-induced Twist1 expression, suggesting the involvement of canonical NF-κB signaling in EMT in these cells." (PMID 37611445, 2023). "Among the top 8 KEGG pathways, cytokine-cytokine receptor interaction, the TNF signaling pathway and the NOD-like receptor signaling pathway are known to play roles in breast cancer." (PMID 37381036, 2023). "Co-treatment with TNF-α and DEX effectively blocked TNF-α-induced apoptosis by inhibiting XIAP, c-IAP1, and c-IAP2 cleavage in human breast cancer cells (MCF-7)." (PMID 37733709, 2023). "TNF-α was also reported to activate the RSK1/2-EphA2 pS897 axis and promote the migration and invasion of breast cancer cells." (PMID 37063424, 2023). "Tumor necrosis factor-alpha (TNF-α) and interferon-γ (IFN-γ) are the most studied pro-inflammatory cytokines in breast cancer." (PMID 36751235, 2023). "We also demonstrated a positive correlation of TNF-α -NF-κB and ATX expression in breast cancer patients using cancer databases." (PMID 38201482, 2023). "Radiotherapy-resistant breast cancer cell line, MDA-MB-231, shows a higher level of inflammasome activation through TNF-α/ATP/P2Y2R pathway than ordinary MDA-MB-231." (PMID 36932407, 2023). "A review by Yu et al26 demonstrated that cytokines such as IL‐1Ra, IL‐6, and TNF‐α increase the permeability and dysfunction of the blood–brain barrier (BBB) and promote the occurrence of depression in breast cancer patients." (PMID 36965094, 2023). "For instance, tumor necrosis factor (TNF-α) and transforming growth factor (TGF-β) produced by stromal cells can affect the invasiveness of breast cancer cells, as can stromal-derived factors (SDF-1), which stimulate the growth of mammary progenitor cells." (PMID 38102637, 2023). "Among the various secreted factors that are thought to be able to induce senescence is the tumor necrosis factor (TNF) alpha produced by CD4 + T helper 1 cells in pancreatic and breast cancer." (PMID 37904250, 2023). "The Timer database, which is used for analyzing the correlation between genes in tumors, showed a positive correlation between TNF-α and ENPP2 expression in different subtypes of breast cancer." (PMID 38201482, 2023). "A large-scale analysis of human breast cancer using the TIMER and GEPIA2 databases showed a positive correlation among TNF-α, RELA, or v-rel avian reticuloendotheliosis viral oncogene homolog A and ATX in breast cancer patients." (PMID 38201482, 2023). "The pro-inflammatory stimulation from TNFα promotes MCP1/CCL2 signaling, which is a mediator of metabolic adaptations in cells and induces increased glycolysis in breast cancer cells." (PMID 37107188, 2023). "ATX expression decreased in 4T1 breast cancer cells in the presence of TNF-α and parthenolide for 4 h as compared to TNF-α alone." (PMID 38201482, 2023).
breast carcinoma (continued). "We confirmed that in breast cancer cells over-expressing ETV7, the repression of TNFRSF1A decreased the activation of NF-κB both in the basal state and upon the stimulation with TNF-α." (PMID 37041130, 2023). "Our past studies demonstrated that “TME Stimulation” (estrogen + TNFα + EGF, representing three arms of the tumor microenvironment, TME) has enriched metastasis-forming cancer stem cells (CSCs) in HR+/HER2− human breast cancer cells." (PMID 37190183, 2023). "Previous studies investigating the role of pDCs in breast cancer showed that transforming growth factor-β (TGF-β) and tumor necrosis factor-α (TNF-α) abundant in the tumor microenvironment impaired production of INF-α in pDCs." (PMID 37958800, 2023). "The prometastatic role of TNFα and its involvement in the EMT process required tumor cell migration to establish breast cancer metastasis and its over-expression has often been associated with aggressive cancer behavior and poor prognosis." (PMID 36835413, 2023). "This study was conducted to predict the effect of vitamin D3 supplementation on the serum level changes of vitamin D, TNF-α, TGF-β1, and TAC in patients with breast cancer by ANN method in MATLAB environment." (PMID 38023986, 2023). "Our study suggests that breast cancer patients with psychological distress have worse cognitive functioning based on MMSE and lower quality of life, with higher levels of IL‐1β, TNF‐α, and IL‐4." (PMID 36965094, 2023). "The research on breast cancer cell has demonstrated that APS can trigger the release of NO and tumor necrosis factor (TNF) from macrophages, possibly by activating of the TLR4-mediated MyD88-dependent signaling pathway, which directly blocks tumor growth." (PMID 37741920, 2023). "Increased KLRB1 expression levels were correlated with inhibition of breast cancer cell proliferation, migration, and invasion, as well as promotion of cell apoptosis, possible through regulation of the NF-κB, PI3K/AKT, and TNF signaling pathways." (PMID 37988189, 2023). "In an orthotopic mammary tumor model, CD8 + T cells displayed increased production of granzyme B, IL-2, and TNF-a at higher doses of CIRT while high-dose photon therapy did not induce secretion of these cytokines from CD8 + tumor-infiltrating lymphocytes." (PMID 36138265, 2023). "The proteins determined by SDS–PAGE to be expressed in mammary tissues in the rat model of DMBA-induced mammary cancer were thought to be HER-2, Nischarin, COX-2, Albumine, Vimentin, Actin, TNF-α, p16, and FABP3." (PMID 39070120, 2023). "EPNE significantly downregulated the level of inflammatory markers such as TNF-α, and IL-6 as compared to groups of the combination of ER + PTX, ER, and PTX alone in DMBA induced breast cancer group." (PMID 36330087, 2022). "Therefore, this study investigated the effect of combined detection of serum TNF-α, TSH, and p185 protein expression levels in breast cancer patients on the diagnostic sensitivity and specificity, in order to provide relevant theoretical basis for clinical diagnosis of breast cancer." (PMID 35783155, 2022). "GBP-2 also inhibits the TNF-α induction of matrix metalloproteinase-9 (MMP-9), known to play a role in breast cancer invasion." (PMID 35681772, 2022). "Some studies have shown that TNF signaling pathway contributes to the development of drug resistance in NSCLC, breast cancer, and clear cell renal cell carcinoma." (PMID 35372081, 2022). "Some studies have shown that in the breast cancer model mice, the HS group can significantly increase the tumor inhibition rate, serum INF–γ and IL-2 levels, and decrease serum TNF-α level." (PMID 35707465, 2022). "At the same time, individual treatment of TRAIL and TNFα in MCF7 and MDA-MB-231 cell lines displayed an increase in 10–50% of fluorescent intensity in both breast cancer cell lines." (PMID 36358282, 2022). "Estrogen dependent regulations of TNFSF2 (TNF-α) and TNF-R2 were corroborated in ER+ breast cancer in mice." (PMID 35432372, 2022).
breast carcinoma (continued). "As a result, G9a silences the expression of TNF and inhibits RIPK3-dependent necroptosis; thus, it promotes breast cancer cell survival and relapse." (PMID 35455671, 2022). "In addition to these cancer-specific gene sets, the F1 and F2 populations were also significantly enriched for TNFα, MAPK, IL-1 7, ErbB, HIF- 1, RAS, RAP 1, PI3K-AKT, and mTOR signaling pathways, all of which have previously associated with breast cancer metastasis." (PMID 35614362, 2022). "Cytokines, such as interferons (IFNs- α, -β, and –γ), interleukins (ILs-2, -6, and -10), and tumor necrosis factor (TNF-α), play an important role in various types of cancer, especially in breast cancer." (PMID 36544523, 2022). "Together, these findings indicate that TNF-α and IFN-γ produced by TSLP-stimulated inflammatory Th2 cells play a key role in providing antitumor immunity against advanced breast cancer." (PMID 36467403, 2022). "At present, there are few clinical reports on the combined detection of serum TNF-α, TSH, and p185 protein in breast cancer." (PMID 35783155, 2022). "Except for the five genes ITPK1, RIPK3, STAT3, TNF, and FASLG, the remaining 62 genes showed significant differences in expression between breast cancer and normal breast samples." (PMID 36675706, 2022). "In the 4T1 breast cancer model, a higher frequency of CD4+ and CD8+ T cells producing IFNγ, TNFα, or IL-2 was found in mice treated with T. usneoides." (PMID 36358804, 2022). "Macrophage TNF and TGFβ1 present within co-cultures have also been shown to increase the migration of MDA-231 breast cancer cells in a 3D culture model through MMP1 and MT1-MMP, respectively." (PMID 35359423, 2022). "For example, EMT in breast cancer cells is regulated by the TGF-β/SMAD pathway and activated by TNF-α/NF-kB/Twist, both of which synergistically promote breast cancer cell migration and metastasis." (PMID 35965509, 2022). "In summary, LPS sensitizes the therapeutic response of both triple-negative and ER+ breast cancer to IAP antagonist therapy by inducing rapid apoptosis of the cancer cells through TLR4- and MyD88-mediated production of TNFα." (PMID 36119107, 2022). "In our study, TNF-alpha mRNA expression was significantly upregulated after CHCP treatment suggesting TNF is involved in both induction of apoptosis and in the survival of breast cancer cells after CHCP treatment." (PMID 35260587, 2022). "A recent study demonstrated that Chinese propolis (25, 50 & 100 μg/ml) treatment inhibits cell proliferation by targeting glycolysis enzymes and proinflammatory cytokines including TNF-α, IL-6, and NLRP3 in the breast cancer cells." (PMID 35754701, 2022). "In contrast, in MDA-MB-231 breast cancer cells, it was demonstrated that PIMT was stimulated by a co-treatment with TGF-β1/TNF-α, which also increased mRNA levels of EMT markers including those of Snail, Slug, MMP-2, MMP-9, and Fibronectin." (PMID 35628507, 2022). "A variety of breast cancer cells were selected and transfected with ILK or shILK, as well as treated with GDC-0941, OSU-T315, or TNF-α antibody for the in vitro studies." (PMID 35477364, 2022). "On the other hand, since TNF and NF‐κB signaling have been reported to affect ER+ and HER2+ breast cancer." (PMID 34197030, 2022). "In conclusion, SIRT6 regulated the migration and invasion of breast cancer cells in vitro and played an essential role in TPA- or TNF-α-induced MMP-9 expression." (PMID 35840633, 2022). "Bouchard and colleagues discovered the proinflammatory cytokines, including interleukin-1β (IL-1β) and tumor necrosis factor-α (TNF-α), to be positively correlated with depressed mood in patients with breast cancer." (PMID 35757220, 2022). "MTT assay was performed with different concentrations of TRAIL and TNFα treatment alone and in combination with BV6 (1 μM) to investigate its antitumor activity and cell viability on the breast cancer cells MCF7 and MDA-MB-231." (PMID 36358282, 2022).